IL10 (interleukin 10)
Diseases named in the same sentence as IL10 in open-access papers (continued):
Sharing a sentence is not in itself a finding about the gene and the disease.
colitis (continued). "For instance, PG derived from Lactobacillus salivarius alleviates colitis in an IL-10-dependent manner by promoting CD103+ regulatory dendritic cells (DCs) and Treg cells." (PMID 41511071, 2026). "After the onset of colitis, IL-10−/− mice have a higher secretion of inflammatory cytokines than wild-type mice, including TNF-α, IL-1β, IL-6, and IFN-γ." (PMID 40732952, 2025). "Il10−/− (n = 17), Il10−/− × Gpr4−/− (n = 13), Il10−/− × Ogr1−/− (n = 10), and Il10−/− × Gpr4−/− × Ogr1−/− (n = 10) developed colitis after approximately 190 days." (PMID 40004018, 2025). "IL-10 production was lower in the TNBS-induced colitis group, but the level was reversed when larval antigen extract was administered either before or after TNBS." (PMID 40830617, 2025). "It suppressed the pro-inflammatory tumor necrosis factor-alpha (TNF-α) and upregulated the anti-inflammatory interleukin-10 (IL-10), both of which were dysregulated by colitis (p < 0.0001)." (PMID 41465478, 2025). "Collectively, our results demonstrate that LGG triggers an IL-10–based autocrine regulatory loop in monocytes to suppress DSS-induced colitis." (PMID 39895628, 2025). "In summary, our findings suggest that the assessment of gut microbiota rhythmicity and composition has the potential to predict the colitis development of IL-10-/- mice." (PMID 39843997, 2025). "IL-22–dependent pathophysiology in A20ZF7 mice also appears distinct from that seen in Treg- and IL-10–deficient mice in that A20ZF7 mice develop proximal enteritis, while the latter models predominantly develop colitis." (PMID 40892518, 2025). "Inversely, M2 exerts a protective effect on the intestinal mucosa by secreting anti-inflammatory factors (such as IL-10), and promoting M2 polarization can effectively alleviate colitis." (PMID 40079012, 2025). "It is thus conceivable that STING does contribute to the regulation of IL-10 expression in monocytes during colitis." (PMID 39895628, 2025). "Further validation of the efficacy of Wc1982 in complementary IBD models—such as trinitrobenzenesulfonic acid-induced colitis and IL-10−/− mice would be useful." (PMID 40356657, 2025). "In a particular study, mononuclear phagocytes (MNPs), a population of myeloid cells, including monocytes, macrophages, and DCs, has been reported to produce IL-10 in the context of colitis." (PMID 39895628, 2025). "In IL-10 knockout mice, administration of the zonulin inhibitor AT-1001 markedly reduced permeability and ameliorated colitis." (PMID 41233834, 2025). "E. faecalis OG1RFSS was used to induce colitis in Gsta4−/− and Il10−/−/Gsta4−/− mice by orogastric gavage." (PMID 39819335, 2025). "The culture supernatant of A. muciniphila alleviated spontaneous colitis in IL-10−/− mice by suppressing pro-inflammatory cytokines, enhancing anti-inflammatory mediators, and strengthening epithelial barrier function." (PMID 41333470, 2025). "E4BP4 and IL-10 double-knockout mice develop severe early-onset colitis and show upregulated IL-12p40 expression." (PMID 40332348, 2025). "This importance is underscored by the fact that when IL-10 is selectively deleted from Tregs through genetic manipulation, spontaneous colitis develops." (PMID 40352719, 2025). "In inflamed IL-10−/− mice, the reassembled microbiota became more aggressive, thereby resulting in more severe colitis upon serial transplantation to other IL-10−/− mice, in contrast to the distinct microbiota reassembled in non-inflamed WT hosts." (PMID 41306971, 2025). "Increased NO produced by MDSCs was shown to exacerbate colitis and promote death of Il-10−/− mice with colitis, though those MDSCs remained suppressive to CD4+ T cells." (PMID 40244120, 2025). "The proof-of-concept L. lactis strain that secretes IL-10 substantially reduced colitis in mice and inspired numerous subsequent projects." (PMID 40767874, 2025).
colitis (continued). "Of interest was that the population of monocytes in MLNs did not significantly change upon different treatments, inferring a key role of LGG in upregulating IL-10 expression in monocytes during DSS-induced colitis." (PMID 39895628, 2025). "In this regard, we also explored that AT-MSCs targeted delivery of IL-10 can significantly alleviate colitis in DSS-induced colitis mouse models." (PMID 39990215, 2025). "Next, we successfully delivered BMP inhibitor Grem1 and anti-inflammatory factor IL-10 to inflammatory colon tissues by AT-MSCs and reduced experimental colitis." (PMID 39990215, 2025). "paracasei L9 expressing Amuc_1100 protein, mRNA levels of pro-inflammatory cytokines (IL-6, TNF-α, and IL-1β) and anti-inflammatory cytokines (IL-4 and IL-10) were measured in colon tissues of DSS-induced colitis mice." (PMID 41515240, 2025). "AhR activation has been linked to the alleviation of colitis by reducing inflammatory cytokines like IL‐1β, IL‐6, and TNF‐α, while enhancing anti‐inflammatory cytokines, such as IL‐4, IL‐10, and IL‐22, and strengthening the intestinal epithelial barrier." (PMID 39836604, 2025). "Pro-inflammatory cytokines (IL-1β, IL-6, TNF-α) were markedly elevated in the Colitis group, while anti-inflammatory IL-10 was suppressed (p < 0.01)." (PMID 40574090, 2025). "Studies have indicated that Clostridium_sensu_stricto_13 can reduce inflammation by producing IL-10 and can induce the accumulation and differentiation of Treg cells, thereby alleviating colitis and allergic diarrhea in mice." (PMID 39859161, 2025). "For instance, L. lactis was engineered to secrete human IL-10 (using a leader peptide) to treat colitis." (PMID 40767874, 2025). "GUT−103 was tested for its efficacy in an IL10-/- colitis model in which colitis was induced via inoculation with Escherichia coli,Enterococcus faecalis, and Ruminococcus gnavus (EER)." (PMID 41239968, 2025). "Modulating the Treg/Th2 response by decreasing proinflammatory cytokines such as TNFα, IL-6, IL-1β, IL-18, IL-22, IL-9 and increasing anti-inflammatory cytokines IL-10 and IL-4 in mice colitis model." (PMID 41208998, 2025). "To further determine the role of epithelial NFAT5 in spontaneous colitis, we generated conditional-KO Il10–/–Nfat5IEC-KO and their Il10–/–Nfat5fl/fl mice." (PMID 40663408, 2025). "Mirroring these results, also in the murine ileitis model (TnfΔARE) and colitis model (IL-10-/-) Pyy expression was reduced in inflammation-affected intestinal tissues." (PMID 41047099, 2025). "To study the effects of combined loss of Gpr4 Ogr1 in IBD we used the well-established acute dextran sodium sulfate (DSS) and spontaneous Il10−/− murine colitis models." (PMID 40004018, 2025). "IL-10 is particularly relevant in IBD, as evidenced by the spontaneous development of colitis in Il10-/- and Il10Rb-/- mice and the correlation of SNPs in IL10 with the early onset of colitis." (PMID 40243612, 2025). "Conversely, the anti-inflammatory cytokine IL-10—produced by Th2 cells—alleviates inflammation by inhibiting pro-inflammatory cytokine production and plays a protective role in colitis models." (PMID 41008979, 2025). "In this study, we utilized IL-10 knockout mice, a model of spontaneous colitis, to investigate the impact of PM2.5 exposure on the gastrointestinal tract." (PMID 40868077, 2025). "Oral supplementation with L. johnsonii alleviates colitis by specifically increasing the proportion of intestinal macrophages and the secretion of IL-10." (PMID 40292216, 2025). "These questions as well as others about the inconsistent effects of clock disruption on colitis in the IL-10−/− mice should be further studied in the future." (PMID 39843997, 2025). "We also report the existence of an IL-10–based autocrine regulatory loop induced by LGG in the context of colitis." (PMID 39895628, 2025). "In mice, the oral administration of Lactobacillus-secreted IL-10 reduced the incidence of DSS-induced colitis by 50%." (PMID 40361597, 2025).
colitis (continued). "IL-10-secreting B cells, a regulatory B cell subtype, have been shown to ameliorate T cell-mediated colitis." (PMID 40331987, 2025). "But the NLRP6 played a crucial role in protecting IL-10-/- mice from colitis through restricting the colonization of A. muciniphila in an IL-18-dependent manner." (PMID 41488633, 2025). "In inflammatory bowel disease (IBD), this shift reduces colonic inflammation and promotes mucosal healing, as evidenced by decreased TNF-α and increased IL-10 levels in murine colitis models." (PMID 40809065, 2025). "Except for lipid-related molecules, peptidoglycan (PGN), polysaccharide purified from Lactobacillus salivarius Ls33, rescued mice from colitis in an IL-10-dependent manner." (PMID 40612235, 2025). "CREB deficient Tregs were highly suppressive in vitro and prevented disease activity in a CD4 T cell mediated transfer colitis in an IL-10 dependent way." (PMID 40777015, 2025). "It has been observed that IL-10 can alleviate symptoms of colitis when the gut microbiota is stimulated to increase the number of macrophages capable of producing IL-10." (PMID 39940655, 2025). "In mice, Gpr4 deficiency protects against inflammation and fibrosis in the spontaneous interleukin 10 knockout (Il10‐/‐) colitis model." (PMID 40397803, 2025). "The extract downregulated pro-inflammatory cytokines (IL-4, IFN-γ, IL-17, and TGF-β) and upregulated the level of the anti-inflammatory cytokine IL-10, significantly reducing the severity of colitis and improving colonic morphology." (PMID 40417008, 2025). "In a previous study, L. gasseri JM1 intake suppressed the expression of inflammatory cytokines such as TNF-α and increased the expression of anti-inflammatory cytokines such as IL-10, thereby alleviating intestinal inflammation in a mouse model of colitis." (PMID 40002326, 2025). "Mounting evidence highlights the importance of IL-10 and its signaling in the inhibition of proinflammatory cytokines in both human and mouse colitis." (PMID 39895628, 2025). "The serum level of IL-10 was significantly increased following the administration of AVCP in colitis mice." (PMID 40507195, 2025). "We thus reasoned that LGG induction of IL-10 in monocytes was specific to colitis or select inflammatory stress." (PMID 39895628, 2025). "Interleukin-10 knockout (IL-10−/−) mice are a well-established model of spontaneous colitis due to impaired anti-inflammatory cytokine signaling and disrupted immune regulation." (PMID 41333470, 2025). "Of these, the regulatory cytokine IL-10 plays a very important role in intestinal homeostasis and suppression of colitis." (PMID 40014218, 2025). "In conclusion, we demonstrate that the culture supernatant of A.m alleviated colitis in IL-10−/− mice by suppressing pro-inflammatory cytokines, enhancing anti-inflammatory mediators, and upregulating epithelial tight junction proteins ZO-1 and occludin." (PMID 41333470, 2025). "This study further supports this inverse relationship between IL-10 and NO synthesis, highlighting IL-10’s role as a critical modulator of inflammatory responses in colitis." (PMID 40830617, 2025). "The present study demonstrated that SS18‐50‐H treatment resulted in a reduction in mRNA expression of TNF‐α, COX‐2, IL‐10, and IL‐6 to levels within the normal range in colitis mice." (PMID 39803293, 2025). "In immunologically humanized HuCD34-NCG mice infected with toxin B-expressing C. difficile ribotype 017, citrulline ameliorated colitis with increased human IL-10 expression in colonic macrophages." (PMID 39923847, 2025). "Portulaca oleracea-derived ELNs target the inflammatory sites in mice with colitis, inhibit the expression of pro-inflammatory cytokines, and increase the level of the anti-inflammatory cytokine IL-10, thereby alleviating colitis." (PMID 40076875, 2025). "Experimental studies have revealed that the outcome of MNV-triggered colitis in IL10 -/- (IL10 null) mice is shaped by the microbial context." (PMID 41020029, 2025).
colitis (continued). "To investigate the impact of aging-associated dysbiosis on colitis development, we employed fecal microbiota transplantation (FMT) in wild-type and IL-10-deficient mice." (PMID 40596758, 2025). "The results of this study indicate that Pediococcus pentosaceus M6 can reduce the expression of IL-6 and IL-1β and increase the expression of IL-10, suggesting that Pediococcus pentosaceus M6 can effectively alleviate the progression of colitis in mice." (PMID 40431130, 2025). "In IL-10-/-mice, a well-established model of spontaneous colitis, impaired H2S synthesis is involved in the exacerbation of colitis associated with hyperhomocysteinemia." (PMID 40948782, 2025). "Taken together, KAR ameliorates colitis by inhibiting the differentiation of Th17 cells and upregulating IL-10 secretion, thereby suppressing mucosal inflammation in IBD." (PMID 40375985, 2025). "Given that the DSS colitis model is primarily driven by macrophages, we evaluated evacetrapib in a T-cell–dominated IL-10 knockout mouse model." (PMID 40484317, 2025). "Ameliorated colitis through AhR signaling activation, increased the expression of anti-inflammatory cytokines, and resulted in the expansion of IL-10-producing CD4+ T cells and IL-22-producing CD3−RORγt+ cells, but not CD4+Foxp3+ regulatory T cells." (PMID 40756994, 2025). "Coupling of the biosensor with the production of the anti‐inflammatory cytokine IL10 allowed for the resolution of chemically induced colitis, demonstrating the ability of the biosensor to sense and respond to disease." (PMID 40323169, 2025). "More importantly, our findings demonstrate that IL-10 production by an immune cell population (Ly6C+ monocytes) is sufficient to prevent colitis." (PMID 39895628, 2025). "Consistently, the transcript levels of Ifn‐γ, Tbx21 and Tnf‐α were elevated while Foxp3 and Il10 levels were decreased of TNBS‐induced Atg7ΔCD4 colitis mice relative to littermate controls born with Atg7fl/fl." (PMID 40887825, 2025). "Genetically engineered animal models employ IL‐10 global knockout mice as IL‐10 being an anti‐inflammatory cytokine, has a beneficial effect on colitis." (PMID 40568744, 2025). "Bacteroidetes, a dominant intestinal phylum, interact with T cells to promote IL-10 secretion, providing protection against colitis." (PMID 40002949, 2025). "We designed an inflammatory bowel disease SynCom of 10 members that successfully induced colitis in gnotobiotic IL10-/- mice, demonstrating the potential of this method to model disease-associated microbiomes." (PMID 40972887, 2025). "The IL-10−/− mouse is a widely used model of chronic, microbiota-driven colitis that shares key features with Crohn’s disease." (PMID 41333470, 2025). "Fecal samples were collected before and at 2 and 14 weeks after cohousing and intestinal tissue samples were harvested at the end of the experiments or at the time of sacrifice for IL-10-/- mice that developed severe colitis." (PMID 39843997, 2025). "The administration of F. saccharivorans improved murine colitis and induced interleukin-10 production in lamina propria mononuclear cells in both colitis model mice and UC patients, suggesting its potential as a novel UC treatment." (PMID 40725792, 2025). "The present data also highlighted the potential role of Interleukin-10 (IL-10) in experimental colitis, with significant correlations with nitric oxide levels in the protective pattern of T. spiralis larval antigen extract." (PMID 40830617, 2025). "Monocytic IL-10 is predominantly responsible for the LGG-mediated protective effect against colitis." (PMID 39895628, 2025). "Increasing experimental data demonstrate that exposure to a certain helminth such as T. spiralis, Hymenolepis diminuta, and Schistosoma mansoni can potently prevent or attenuate colitis by increasing IL-10 production." (PMID 40014218, 2025). "Nuciferine was found to alleviate DSS-induced colitis in mice by inhibiting the release of pro-inflammatory factors such as IL-1 and IL-10." (PMID 40699713, 2025).
colitis (continued). "Innovative research conducted two decades prior offered initial proof-of-concept; for example, a 2022 study engineered Lactococcus lactis to secrete human interleukin-10, thereby successfully alleviating colitis in murine models." (PMID 40767874, 2025). "The observations in IL-10−/− mice led to therapeutic trials of IL-10 in other models of colitis, showing that systemic IL-10 administration can prevent intestinal inflammation by down regulating the intestinal pro-inflammatory Th1 response." (PMID 41463087, 2025). "While T cells produce proinflammatory cytokines, which contribute to the induction of colitis, they also produce anti-inflammatory cytokines, including IL-10 and IL-22, which inhibit colitis development." (PMID 41321963, 2025). "EVs derived from dendritic cells treated with IL‐10 decreased the severity of experimental colitis in mice and improved epithelial barrier function dependent on EV miR‐146b." (PMID 40165585, 2025). "Mice injected with EVs from the roundworm, Nippostrongylus brasiliensis showed reduced colitis, likely due to miRNAs that suppress proinflammatory cytokines and promoted the production of anti‐inflammatory IL‐10." (PMID 40165585, 2025). "For characterizing the effect of inflammation on EECs numbers in detail, we took advantage of the heterogeneity in the grade of CD-like inflammation in TnfΔARE mice and of colitis in IL-10-/- mice." (PMID 41047099, 2025). "The largest group comprised animal studies (n = 29), including various mouse models (DSS-induced colitis, IL-10 knockout, Rag1 knockout, and Casp8ΔIEC mice)." (PMID 40647225, 2025). "IL-10−/− mice are a widely used model for studying intestinal inflammation, as they typically develop spontaneous colitis between 7 and 15 weeks of age." (PMID 41333470, 2025). "Taken together, these findings highlight the critical role of monocytic IL-10 in LGG-mediated colitis control." (PMID 39895628, 2025). "To further confirm the role of monocytic IL-10 in LGG-mediated protective effects during colitis, we knocked down Il10 using siRNA in bone marrow–derived monocytes to generate Il10-KD BM monocytes." (PMID 39895628, 2025). "For instance, in the context of IBD, Blimp-1-mediated IL-10 production by CD4+ T cells has been demonstrated to suppress colitis." (PMID 40375985, 2025). "When OPN/IL-10 and IL-10 were then compared, researchers observed a faster development of colitis in OPN/IL-10 mice." (PMID 40565331, 2025). "We demonstrate inconsistent effects of clock disruption on experimental colitis, but extended survival, improved intestinal inflammation and gut microbiota rhythmicity in IL-10-/- mice after TRF." (PMID 39843997, 2025). "E. faecium strains isolated from the feces of UC patients were shown to promote colitis pathology scores and inflammatory cytokine expression in IL-10 knockout mice, compared to strains isolated from healthy individuals." (PMID 40292216, 2025). "While IL-10 is an important regulator in preventing pro-inflammatory responses, Il10-/- mice display faster pathogen clearance and attenuated colitis post CR infection." (PMID 40591723, 2025). "TsAES demonstrates tumor growth factor-beta-like activity, driving pTreg differentiation and suppressing DSS-induced colitis with IL-10 upregulation." (PMID 40597393, 2025). "High salt diet (HSD) exacerbates colitis in the Il10–/– colitis model by activating p38 MAPK and SGK1 in dendritic cells." (PMID 40121360, 2025). "This study aims to determine how dealcoholized muscadine wine (DMW) affects the development of colitis and gut microbiome in IL-10−/− mice, compared to wild types (WT)." (PMID 40732952, 2025). "To assess the potential of TRF to restore disrupted intestinal clock and microbiota phenotypes and delay the development of intestinal inflammation and colitis, we compared IL-10-/- and WT mice subjected to TRF or ad libitum (AL) feeding from E.3." (PMID 39843997, 2025).